EGFR (epidermal growth factor receptor)
Diseases named in the same sentence as EGFR in open-access papers (continued):
Sharing a sentence is not in itself a finding about the gene and the disease.
tumor (continued). "Similar to AMT-562, DB-1310 was also shown to synergize with osimertinib in EGFR-mutant NSCLC cell line xenografts and dramatically suppressed tumor growth in an osimertinib-resistant NSCLC PDX model." (PMID 39065587, 2024). "Preclinically, ABT-414 promoted tumor growth inhibition (TGI) and regression superior to ABT-806 in several EGFR-overexpressing xenografts." (PMID 39065587, 2024). "The EGFR signaling pathway is often dysregulated in NSCLC, leading to increased tumor growth and resistance to therapy." (PMID 38981473, 2024). "Hence, in this context, targeting of EGFR-positive BRAFi-resistant CM cells by combined treatment with cetuximab and ICIs might appear an extremely attractive option that would take advantage of the concomitant action on tumor and immune cells." (PMID 38510242, 2024). "It has been discovered that the over-activation of the EGFR family of RTK, which includes EGFR (EGFR/HER-1 or ERBB-1), HER-2 (Neu or ERBB-2), HER-3 (ERBB-3), and HER-4 (ERBB-4), promotes the growth and progression of numerous tumor types." (PMID 39130630, 2024). "FOM and labeling with PE-conjugated anti-EGFR AY13 (3-day treatment) and anti-EpCAM 9C4 (6-day treatment) mAbs identified additional CAM specimens bearing macroscopically invisible vital tumor microresidues." (PMID 38883274, 2024). "Activation of AXL often accompanies the occurrence of tumor cell EMT, promoting resistance of NSCLC cells to EGFR TKIs." (PMID 39582541, 2024). "In combination with lazertinib, a third-generation EGFR TKI, it targets EGFR at both the extracellular and catalytic domains, demonstrating synergistic inhibition of tumor growth." (PMID 39199633, 2024). "Subsequent activation of receptor tyrosine kinase signaling (e.g., epidermal growth factor receptor (EGFR)) and/or activation of downstream signaling pathways such as phosphoinositide-3-kinase (PI3K) drives proliferation and tumor growth." (PMID 39126067, 2024). "The lack of significant association between EGFR expression and tumor grade in the current study may be attributed to differences in the selection of study groups, pre-analytical procedures, the type of primary antibodies used, the score used for EGFR interpretation, and the small sample size." (PMID 39405290, 2024). "The tetrazine fragment was conjugated with tumor-specific ligands (galactose derivative and GE11 peptide specific to EGFR)." (PMID 38675140, 2024). "Overexpression of EGFR and HER3 increases HER2–EGFR and HER2–HER3 heterodimer formation, allowing tumor cells to reactivate HER2 signaling with only a few HER2 molecules present." (PMID 39199625, 2024). "T7E1 digestion assay results demonstrated that ANC@RNP achieved more potent activity at EGFR and PLK1 gene sites versus non‐targeted NC@RNP after 48 h incubation in U87MG cells, signifying the importance of ApoE‐ligand in tumor targeting." (PMID 38943253, 2024). "Engineered exosomes loaded with miR-let-7a efficiently target Epidermal Growth Factor Receptor (EGFR) -expressing cells, resulting in tumor growth inhibition." (PMID 38780753, 2024). "Based on this mechanism, one of the anticancer mechanisms of ALA involves reducing tumor cell activity at the TKR level and inhibiting tumor cell proliferation mediated by the oncogenes ERBB1/EGFR and ERBB2/HER2." (PMID 39199143, 2024). "aCD3-a EGFR SMART-Exos exhibited highly potent and specific anti-tumor activity in vitro and in vivo." (PMID 38280847, 2024). "These phenomena were less evidently seen in the LUSC model, as there was less abundant co-expression of EGFR and MET in the tumor." (PMID 38916448, 2024). "The EGFR H-Score and PD-L1 H-Score in OSCC and para tumor tissues were 141.2 vs. 67.19 and 116.2 vs. 69.66, respectively (**** P < 0.0001)." (PMID 39183296, 2024). "The treatment of NSCLC cell lines with EGFR TKI resulted in Axl overexpression, the viability of tumour cells, and the inhibition of apoptotic pathways." (PMID 38672690, 2024).
tumor (continued). "Also, there were a number of other signaling molecules, EGFR in particular, that were more heavily phosphorylated in ERK inhibitor/GBM EV-treated astrocytes, suggesting that these altered signaling cascades may cause astrocytes to become more tumor-like." (PMID 39585062, 2024). "RNA pulldown experiments and RNA immunoprecipitation (RIP) assays showed that LINC00152 interacted with EGF receptor (EGFR) to constitutively activate EGFR and subsequently, the PI3K/AKT signaling pathway, leading to increased tumor cell proliferation." (PMID 39161590, 2024). "GBM is characterized by intense expression of the epidermal growth factor receptor (EGFR or HER1) on the membrane, including mutant tumor-specific forms, such as EGFRvIII and others." (PMID 39598559, 2024). "The expression levels of EGFR and PD-L1 in OSCC tumor tissues were also observed based on the fluorescence intensity produced by excitation light irradiation at 665 nm and 785 nm." (PMID 39183296, 2024). "Among 279 gene pairs with tumor type-specific significant ED in LUAD, we selected 19 gene pairs including EGFR as either context genes or their partner genes." (PMID 39160568, 2024). "BINI and ENCO have been shown to promote epidermal growth factor receptor (EGFR)-mediated cell proliferation by deactivating the MAPK pathway and tumor growth is inhibited by the co-administration of CET." (PMID 39310595, 2024). "Clinical tumor specimens were subjected to immunohistochemical analysis, enabling the assessment of phospho-EGFR (p-EGFR) expression levels and the infiltration level of CD8+ tumor-infiltrating lymphocytes (TILs)." (PMID 39062533, 2024). "Simultaneous inhibition of EGFR and α5β1 integrin signaling by αEGFR-E-P125A is a promising strategy for the inhibition of VM, tumor growth, motility, and metastasis in TNBC and other EGFR-overexpressing tumors." (PMID 38315147, 2024). "We performed single-cell analysis based on data from an independent study to validate the co-expression of EGFR and MUC1 in cancer cells, as well as in other cells of the tumor microenvironment." (PMID 39664199, 2024). "This approach has the potential to harness DUSP22 expression, enabling the simultaneous targeting of EGFR and ERK1/2 pathways, resulting in the suppression of TKI-resistant or DUSP22-deleted tumor growth." (PMID 38877005, 2024). "Our findings indicate that HDCA suppresses the EREG/EGFR signaling route by activating FXR, thereby hindering the growth of CRC cells and demonstrating a tumor-inhibiting effect in CRC." (PMID 39834394, 2024). "Examples for on-target/off-tumor reactivity are CAR T cells targeting ErbB2/her2, EGFR, and CAIX-specific CAR T cells." (PMID 39594628, 2024). "The most common targets of the RTK pathway are EGFR and PTEN, the former acting in an oncogenic role while the latter acting as a tumor suppressor." (PMID 38474286, 2024). "EGFR expression was observed in all 30 (100%) OSCC tissue microarrays, primarily localized on the membrane of the tumor cells." (PMID 39594688, 2024). "To explore the efficacy and specificity of tumor-targeting ligand for NPC-positive cells, we developed Z239-1907 affibody shown to possess high-binding affinity for Axl and EGFR." (PMID 39594573, 2024). "Although TKI drugs inhibit downstream signaling pathways of driver genes, key signaling pathways within tumor cells can still be persistently activated through bypass routes such as MET gene amplification, EGFR gene amplification, and AXL activation." (PMID 39582541, 2024). "The EGFR/STAT3 signal axis is a relatively well-defined cytokine and growth factor signal axis, and STAT3 has long since been shown to promote tumor growth." (PMID 39338323, 2024). "During early EGFR-TKI treatment, increased CXCL10 levels stimulated oncogenic signaling in persisting tumor cells, contributing to EGFR-TKI resistance through autocrine and paracrine pathways." (PMID 39114657, 2024).
tumor (continued). "The results of the expression of the protumour factor GHRH in PC-3 tumours showed that after treatment with the GHRH-R antagonist and the EGFR inhibitor, there was a decrease in expression." (PMID 39456984, 2024). "Tuba-seq analysis of DNA extracted from bulk tumor-bearing lungs allowed us to quantify tumor burden and size across mouse genotypes, and thus determine the tumorigenic potential of BRAF V600E and EGFR L858R relative to KRAS G12C and KRAS G12D." (PMID 37828026, 2023). "It has been reported that RUNX1 regulated tumor function by activating downstream STAT3 and transcriptionally regulating EGFR gene expression." (PMID 38057816, 2023). "Upon specifically recognizing cancer cells with high levels of wild-type EGFR, the drug binds with high affinity to the mutant EGFR VIII, thereby exerting anti-tumor effects by inhibiting the EGFR/ERK pathway." (PMID 37305567, 2023). "We showed that supplementing the current standard-of-care combination of the BRAF inhibitor encorafenib plus an anti-EGFR antibody (panitumumab) with the FDA-approved COX2 inhibitor celecoxib significantly and consistently improved tumor growth inhibition." (PMID 36759733, 2023). "This downregulation of miR-665 leads to increased expression of oncogenes like EGFR, BRAF, KRAS, and MYC, which promote tumor cell migration, invasion, and proliferation." (PMID 37894282, 2023). "Recently, carboxymethyl chitosan, a water-soluble derivative of chitosan, was utilized to prepare multifunctional micelles grafted with an epidermal growth factor receptor (EGFR)-specific ligand, GE11 peptide, for tumor targeting." (PMID 37631235, 2023). "Focus is needed on eliminating the proliferating tumor population through antiproliferative therapies such as temozolomide (TMZ), radiotherapy, and EGFR inhibitors." (PMID 37109434, 2023). "This review summarizes the multiple mechanisms of TAM-mediated EGFR-TKIs resistance in NSCLC, including activation of bypass pathways, inhibition of T cell activity, M2-like polarization, and regulation of tumor cell phenotypes." (PMID 37649478, 2023). "Our group studied the expression of mTOR and EGFR in LSCC cells and their correlation with tumor neo-angiogenesis, in terms of CD105-assessed MVD, and prognosis." (PMID 37445908, 2023). "HERTHENA-Lung01 is a Phase 2 clinical trial (NCT04619004) aimed at evaluating the anti-tumor activity of patritumab deruxtecan in subjects with metastatic or locally advanced NSCLC and an activating EGFR mutant (exon 19 deletion or L858R)." (PMID 38162667, 2023). "We analyzed activated levels in tumor cells from EGFR-driven LUAD and found that only the activated form of NOTCH4 (NICD4) was greatly increased in tumor samples resistant to EGFR TKIs compared with those sensitive to EGFR TKIs." (PMID 37268635, 2023). "Our results demonstrate that PLCD1 is a potent tumor suppressor frequently inactivated by promoter methylation in RCC and exerts its tumor suppressive functions via suppressing WNT/β‐catenin and EGFR‐FAK-ERK signaling." (PMID 36849889, 2023). "High levels of ER or EGFR showed a significant correlation with poor overall survival in NSCLC patients, suggesting that the ER‐triggered EGFR signaling axis promotes tumor progression." (PMID 37013960, 2023). "Oncogenic EGFR and PDGFR signaling mechanisms are important in tumor cell proliferation and invasion in GBM, although NF-κB is involved in just a small portion of these receptors’ boosting function." (PMID 38201528, 2023). "To determine the effect of JAC4 in EGFR-mutant LUAD progression in vivo, we created a subcutaneous tumor-bearing mouse model." (PMID 37240137, 2023).
tumor (continued). "Organoids and tumours from patients and transgenic mice were treated with AICAR alone or in combination with JAK and EGFR inhibitors to evaluate treatment effects." (PMID 36810913, 2023). "Together, our findings demonstrate the tumor-suppressive role of JMJD5 in NSCLC and suggest a putative therapeutic strategy for EGFR-related NSCLC by targeting JMJD5 to destabilize EGFR." (PMID 37813845, 2023). "The interactions of EGFR with MUC1 and SNX1 have both been targeted and shown efficacy in animal mouse tumor models." (PMID 37720348, 2023). "High expression of EGFR activates the RAF/MEK/ERK pathway and induces resistance to PLX4032 in tumor cells." (PMID 37996892, 2023). "Lastly, in a future study, a comprehensive pathway analysis using RNA-seq or proteomics on EGFR-TKI-resistant cells and tumor samples would help us characterize the modulations of downstream pathways in further detail." (PMID 37444572, 2023). "Erlotinib suppresses the tumor growth of the human endometrial adenocarcinoma cell line HEC-1A, which expresses high levels of EGFR." (PMID 37601068, 2023). "In this regard, the fluorescence signals of EGFR and CD133 in GBM tissue were investigated to identify the severity of tumor progression and CD133 targeting efficacy, respectively." (PMID 37179387, 2023). "Noted amivantamab actions, include its ability to induce trogocytosis and allocate immune effector cells for eliminating EGFR and MET expressing tumor cells, vis-à-vis antibody-dependent cellular cytotoxicity." (PMID 37970206, 2023). "Given the comparable in vitro performance of WSD-0922 to erlotinib, we next sought to assess the in vivo efficacy of these two EGFR TKIs using GBM12, GBM39, and GBM6 PDX orthotopic and flank tumor models." (PMID 37324218, 2023). "Antibodies that recognize antigens on these tumor cell lines (Raji cell surface antigen CD20; A549 cell surface antigen EGFR) by combination are clinically approved for use and proven to be effective." (PMID 37316891, 2023). "Previous studies have shown that patients with advanced NSCLC carrying EGFR mutations have a poor response to immunotherapy, and a possible mechanism for this poor response is the low expression of PD-L1 or the lack of infiltrating T cells in the tumor microenvironment (TME)." (PMID 37266427, 2023). "MiR-338-3p inhibited EGFR and subsequently activated EYA2, which accelerates BC tumor cell growth and lung metastasis." (PMID 36750914, 2023). "Autophagy induction via SMURF1-mediatd activation of UVRAG was shown to functionally result in autophagic degradation of oncoprotein EGFR and, consequently, suppress HCC cell proliferation and tumor growth." (PMID 36918822, 2023). "We further showed that the SMARCA4R1157W mutant reinforced the transcriptional expression of EGFR and TNS4 to promote the proliferation of CRC cells and patient-derived tumor organoids." (PMID 36922568, 2023). "A significant decrease in EGFR, HER2, and VEGFR receptor expressions of 4NSG-SLN was observed compared to GemHCl treatments in Black’s and White tumor tissues." (PMID 37179357, 2023). "Consistently, co-treating EGFR transgenic mouse lung tumour tissue-derived organoids with osimertinib, VX-509, and AICAR significantly inhibited tumour organoid initiation in 10 days (p < 0.05)." (PMID 36810913, 2023). "We focused on the following tumor-related antigens found in BC: HER2, TROP2, EGFR, CD276, and EpCAM." (PMID 38201595, 2023). "Dysregulation of the EGFR signaling pathway through LLPS-mediated mechanisms can lead to the upregulation of transcription factors, such as c-Myc, and COX-2, promoting tumor growth, invasion, and angiogenesis." (PMID 37580790, 2023). "Consequently, a patient with both EGFR sensitizing mutations and Ras mutations in the tumor may not respond to targeted therapy due to proliferative signal transduction by an active Ras oncoprotein regardless of upstream inhibition of EGFR by a drug." (PMID 38201251, 2023).
tumor (continued). "Amphiregulin (AREG)/epidermal growth factor receptor (EGFR) signaling induces hypoxia-inducible factor-1α (HIF-1α), leading to promotion of T helper 9 (Th9) differentiation and anti-tumor functions." (PMID 36154925, 2023). "CUDC-101 is a potent HDAC inhibitor that synergistically inhibits EGFR/HER2 kinases and attenuates multiple compensatory pathways, such as AKT; it also suppresses the progression of a broad range of tumor types in both in vitro and in vivo xenograft models." (PMID 37566008, 2023). "Alongside others RTKs, EGFR can regulate microRNA-134 in GBM, which acts as a tumor-suppressive center." (PMID 37446288, 2023). "The combination of EGFR and VEGF inhibition has shown efficacy in preclinical setting, finding improved survival and tumor inhibition in mouse models." (PMID 37409250, 2023). "At the protein level, our results showed that EGFR is highly expressed in PTC mainly in the cytoplasm and the plasma membrane of tumor cells." (PMID 37114127, 2023). "In tumor cells, activated Hsp90 influences the physiological functions of client proteins such as AKT, ERK, and EGFR, thereby enhancing their stability and levels of expression." (PMID 37719860, 2023). "Because of the clinical impression, where patients who received the VEGF antibody treatment experienced rapid symptom release and increased tumor regression, we evaluated the difference between the VEGF and EGFR antibody treatments." (PMID 37296862, 2023). "For example, the inactivation of NF1—a positive regulator of KRAS GTP to GDP transition—should shift KRAS proteins into their GTP-bound state and increase tumor number and/or growth in the KRAS G12C-, KRAS G12D- and EGFR-driven tumors." (PMID 37828026, 2023). "For half of the biomarkers (AKT, ALK, BRAF, EGFR, Hedgehog, HER2, KRAS, MSI, NTRK, and ROS1), depending on the tumor type, the response rate ranged from 0 to 100%." (PMID 36639625, 2023). "In the context of EGFR–driven lung tumorigenesis, MIG6, an EGFR–negative regulator, acts as a tumor suppressor by downregulating EGFR signaling, highlighting the emerging research focusing on the interplay between AXL, MIG6 and EGFR in NSCLC." (PMID 37834326, 2023). "In xenograft models overexpressing HER2 (BT474) and EGFR (SKOV-3 and A431), neratinib dose-dependently inhibited tumor growth: almost by ~70–90% in xenografts of BT474, ~30–60% in xenografts of SK-OV-3, and ~32–44% in xenografts of A431." (PMID 38201251, 2023). "Protein interaction network shows that epidermal growth factor receptor [EGRF] and estrogen receptor 1 [ESR1] are tumor drivers and drug targeting factors." (PMID 37542141, 2023). "Among these, EGFR- and MSLN-specific CAR-T cells seem to be more promising than the others due to the antigen’s higher specificity and lower on-target, off-tumor toxicity concerns." (PMID 36765623, 2023). "In tumor cell lines, transient depletion of UBE4B results in increased levels of EGFR and activation of the downstream MAPK/ERK signaling pathway." (PMID 37754259, 2023). "To date, histological studies have indicated that the epidermal growth factor receptor (EGFR) family, including four transmembrane tyrosine kinases, is overexpressed in many tumor tissues." (PMID 37111769, 2023). "However, this discrepancy may indicate the intra‐tumor heterogeneity regarding EGFR amplification." (PMID 37537946, 2023). "The epidermal growth factor receptor (EGFR) gene and its proteins play a key role in promoting CRC tumor growth." (PMID 37875976, 2023). "We next investigated the impact of tumor suppressor gene inactivation on the growth of BRAF V600E- and EGFR L858R-driven lung tumors and compared tumor suppressor effects across all four oncogenic alleles." (PMID 37828026, 2023).